CALCRL (calcitonin receptor like receptor)
Description:
G protein-coupled receptor which specificity is determined by its interaction with receptor-activity-modifying proteins (RAMPs). Together with RAMP1, form the receptor complex for calcitonin-gene-related peptides CALCA/CGRP1 and CALCB/CGRP2. Together with RAMP2 or RAMP3, function as receptor complexes for adrenomedullin (ADM and ADM2). Ligand binding causes a conformation change that triggers signaling via guanine nucleotide-binding proteins (G proteins) and modulates the activity of downstream effectors. Activates cAMP-dependent pathway.
Synonyms: CRLR; CGRPR; LMPHM8
Tractability: Small molecule: an approved drug acts on it; a structure with a bound ligand is known; a high-quality ligand is known; it belongs to a druggable protein family. Antibody: an approved drug acts on it; UniProt places it where antibodies can reach, with high confidence; its Gene Ontology location is reachable by antibodies, with high confidence; UniProt predicts a signal peptide or a membrane-spanning region; the Human Protein Atlas places it where antibodies can reach. PROTAC: ubiquitination databases record sites on it; a small molecule that binds it is known. Other modalities: a drug acting on it is in phase 2 or 3 trials.
Target class: Family B G protein-coupled receptor; Calcitonin gene-related peptide receptor; Peptide receptor (family B GPCR); Calcitonin-like receptor; Membrane receptor
Safety:
Unwanted effects reported when the protein is acted on. In parentheses: how it was acted on, where the effect was seen, and who reports it.
decreased blood calcium (activation, acute dosing; nervous system, cardiovascular, gastrointestinal, blood; source: Lynch et al. (2017))
decreased blood phosphate (activation, acute dosing; nervous system, cardiovascular, gastrointestinal, blood; source: Lynch et al. (2017))
decreased blood pressure (activation, acute dosing; nervous system, cardiovascular, gastrointestinal, blood; source: Lynch et al. (2017))
decreased gastric emptying (activation, acute dosing; nervous system, cardiovascular, gastrointestinal, blood; source: Lynch et al. (2017))
decreased pain (inhibition, acute dosing; nervous system, cardiovascular, gastrointestinal, blood; source: Lynch et al. (2017))
facial flushing (activation, acute dosing; nervous system, cardiovascular, gastrointestinal, blood; source: Lynch et al. (2017))
increased blood glucose (activation, acute dosing; nervous system, cardiovascular, gastrointestinal, blood; source: Lynch et al. (2017))
increased blood pressure (inhibition, acute dosing; nervous system, cardiovascular, gastrointestinal, blood; source: Lynch et al. (2017))
increased cardiac contractility (activation, acute dosing; nervous system, cardiovascular, gastrointestinal, blood; source: Lynch et al. (2017))
increased heart rate (activation, acute dosing; nervous system, cardiovascular, gastrointestinal, blood; source: Lynch et al. (2017))
increased pain (activation, acute dosing; nervous system, cardiovascular, gastrointestinal, blood; source: Lynch et al. (2017))
Gene: Protein-coding gene on chromosome 2 (187,341,946 to 187,448,506, reverse strand). Ensembl gene ENSG00000064989.
Subcellular location: Cell membrane
Subcellular location (Human Protein Atlas): Plasma membrane
Pathways (Reactome):
Signal Transduction: Calcitonin-like ligand receptors; G alpha (s) signalling events
Cellular responses to stimuli: High laminar flow shear stress activates signaling by PIEZO1 and PECAM1:CDH5:KDR in endothelial cells
Gene Ontology:
Molecular function: adrenomedullin binding; adrenomedullin receptor activity; calcitonin gene-related peptide receptor activity; protein binding; G protein-coupled receptor activity; calcitonin receptor activity; transmembrane signaling receptor activity
Biological process: adenylate cyclase-activating G protein-coupled receptor signaling pathway; adrenomedullin receptor signaling pathway; angiogenesis; calcitonin gene-related peptide receptor signaling pathway; calcium ion transport; cellular response to sucrose stimulus; protein transport; receptor internalization; G protein-coupled receptor signaling pathway, coupled to cyclic nucleotide second messenger; cell surface receptor signaling pathway; G protein-coupled receptor signaling pathway
Cellular component: adrenomedullin receptor complex; CGRP receptor complex; cytoplasm; endoplasmic reticulum; endosome; lysosome; plasma membrane; membrane
Genetic constraint (gnomAD): Loss-of-function variants: 19 observed, 39.79 expected, observed/expected ratio (o/e) 0.48, 90% interval 0.33 to 0.7. The upper end of that interval is the gene's LOEUF score, 0.7, which puts it in group 2 of 6, group 1 being the genes least tolerant of losing a copy. Missense variants: 292 observed, 399.02 expected, observed/expected ratio (o/e) 0.73, 90% interval 0.66 to 0.81. Synonymous variants: 126 observed, 133.02 expected, observed/expected ratio (o/e) 0.95, 90% interval 0.82 to 1.1.
Homologues: Orthologues: macaque CALCRL (99% identical), chimpanzee CALCRL (97% identical), rabbit CALCRL (96% identical), pig CALCRL (93% identical), guinea pig CALCRL (90% identical), mouse Calcrl (90% identical), rat Calcrl (89% identical), dog CALCRL (87% identical), tropical clawed frog calcrl (80% identical), zebrafish calcrlb (66% identical). Paralogues in human: CALCR (55% identical), PTH1R (30% identical), VIPR1 (27% identical), SCTR (27% identical), PTH2R (27% identical), GIPR (27% identical), ADCYAP1R1 (26% identical), GCGR (26% identical), GLP2R (25% identical), VIPR2 (25% identical), GLP1R (25% identical), GHRHR (23% identical), and 30 more.
Diseases named in the same sentence as CALCRL in open-access papers:
CALCRL is named in the same sentence as 96 diseases in open-access papers, as found by Europe PMC text mining. Sharing a sentence is not in itself a finding about the gene and the disease. The quoted sentences say what the papers report.
migraine (31 papers, 2014 to 2025). "Receptor activity-modifying protein 1 (RAMP1), a type I transmembrane domain protein, binds the calcitonin receptor-like receptor (CLR) class B GPCR to form the Calcitonin gene-related peptide (CGRP) receptor which is involved in the pathology of migraine." (PMID 37039481, 2023). "Genes mapping to approved or investigational drugs included CALCRL (target of several medications used to manage migraine disorder), LAMC1 (target of ocriplasmin, used to treat vitreomacular traction), and ANGPTL4 (investigational target for hypertriglyceridemia)." (PMID 40874306, 2025). "The neuropeptide CGRP, acting through the G-protein coupled receptor CALCRL and its coreceptor RAMP1, plays a key role in migraines, which has led to the clinical development of several inhibitory compounds." (PMID 31756985, 2019). "Demographics, migraine history, comorbidities, treatment outcomes, and genetic variants in CGRP receptor-related genes (CALCRL and RAMP1) were evaluated for associations with non-response to ERE, defined as a <50% reduction in monthly migraine days." (PMID 41464829, 2025).
acute myeloid leukemia (10 papers, 2019 to 2025). Acute myeloid leukemia (AML) is a group of neoplasms arising from precursor cells committed to the myeloid cell-line differentiation. "High expression of CALCRL has been shown to be associated with poor prognosis in acute myeloid leukemia." (PMID 35087751, 2021). "Recently, high CALCRL expression has been shown to be associated with a poor prognosis in acute myeloid leukemia (AML)." (PMID 31756985, 2019). "It has been published that CGRP has chemotherapy resistance in acute myeloid leukemia (AML) cell lines via the CGRP/CALCRL axis and promotes prostate tumor growth in murine models, possibly via ERKs/STAT3 signaling." (PMID 36582785, 2022). "CALCRL was increased in some tumor types, such as acute myeloid leukemia, Kaposi’s sarcoma, and Ewing sarcoma." (PMID 35087751, 2021). "In acute myeloid leukemia and Ewing sarcoma, the efficacy of some drugs targeting CGRP and its receptors calcitonin receptor-like receptor (CALCRL) and receptor activity-modifying protein 1 (RAMP1) has been verified." (PMID 37347365, 2023). "Since we previously identified high expression of calcitonin receptor like receptor (CRLR) in acute myeloid leukemia (AML) with high EVI1 expression, we here characterized the function of CRLR in hematopoiesis." (PMID 30674976, 2019). "Although there have been no reports of P2RY1 and CALCRL involved in lung diseases and cancer, they all have been demonstrated to play important roles in other cancers, such as bladder cancer, prostate cancer, and acute myeloid leukemia." (PMID 34039311, 2021).
glioma (8 papers, 2013 to 2025). A benign or malignant brain and spinal cord tumor that arises from glial cells (astrocytes, oligodendrocytes, ependymal cells). "CALCRL/RAMP2 (Adrenomedullin 1 (AM1) receptor) and CALCRL/RAMP3 (Adrenomedullin 2 (AM2) receptor) mRNA has been detected in both human glioma biopsies and in GBM cell lines." (PMID 30777055, 2019). "Western blot also showed that the protein levels of CALCRL, SERPINE1, and MMP14 in glioma cells were basically higher than human glioma cells, whereas GABBR1 has the opposite trend, which is consistent with the results qRT-PCR and IHC." (PMID 37488455, 2023). "The western blot results also confirmed the differences of CALCRL, GABBR1, SERPINE1, and MMP14 in normal human astrocyte cell and glioma cells." (PMID 37488455, 2023). "High GNAI, EMP3, TIMP1, ITGA5, and NMI while low PCDH7, CALCRL, and NFKBIA expressions could lead to poor prognoses in glioma patients." (PMID 35647198, 2022). "Amongst the differentially expressed genes, it is interesting to note the over-expression of CALCRL, a G protein-coupled receptor that acts as a receptor for adrenomedullin and calcitonin gene-related peptide (CGRP), and is strongly expressed by in several vascular tumours and types of gliomas." (PMID 25239601, 2014).
leukemia (7 papers, 2021 to 2025). A malignant (clonal) hematologic disorder, involving hematopoietic stem cells and characterized by the presence of primitive or atypical myeloid or lymphoid cells in the bone marrow and the blood. "Recent studies reveal that CALCRL plays a critical role in leukemia." (PMID 41163355, 2025). "In this attractive model and in the dynamic period of post-chemotherapy MRD, CALCRL-positive AML cells belong to this leukemia-regenerating cell subpopulation and CALCRL is essential for the preservation of the LSC potential of primary chemoresistant AML cells." (PMID 33462236, 2021). "CALCRL can regulate the balance between survival and apoptosis of AML cells by maintaining the stemness of leukemia cells." (PMID 41163355, 2025). "Another notable example of highly context-specific co-regulation of signaling axes is the one mediated by CALCR and its close paralog, CALCRL, whose interaction with ADM is a critical factor determining relapse and drug resistance in leukemia." (PMID 38723607, 2024). "A recent paper identified calcitonin receptor-like receptor (CALCRL) is highly expressed in leukemia DTPs and its depletion reduces leukemia stem cell frequency after chemotherapy." (PMID 33807785, 2021). "However, it has been recently reported that CALCRL, the receptor of ADM and CGRP, is also overexpressed in LSC and its genomic ablation impaired the clonogenic capacity of AML cell lines and the frequency of chemotherapy-resistant cells able to initiate leukemia relapse in preclinical models." (PMID 34150648, 2021).
migraine headaches (5 papers, 2020 to 2025). "Importantly, antibodies interfering with CALCRL signaling have recently been approved for the preventive treatment of migraine headaches." (PMID 35342399, 2022).
Sepsis (5 papers, 2012 to 2026). Sepsis is defined as life-threatening organ dysfunction caused by a dysregulated host response to infection. "The peptide adrenomedullin AM, which binds CALCRL, has been implicated in the pathogenesis of sepsis and the immune response." (PMID 37113606, 2023). "Notably, CALCRL downregulation in sepsis disrupts its interaction with RAMP2/3 (receptor activity-modifying proteins), thereby impairing adrenomedullin clearance and compromising its protective anti-inflammatory functions." (PMID 40761792, 2025).
Hypertension (4 papers, 2012 to 2025). The presence of chronic increased pressure in the systemic arterial system. "CALCRL (calcitonin receptor-like) is a multifunctional vasodilator peptide that was persistently upregulated in aged rats whereas Cyp11b1 is associated with essential hypertension and had decreased levels in both age groups." (PMID 23251410, 2012). "Phenome‐wide MR analysis indicated that CALCRL is correlated with benign breast neoplasms, and HSD17B12 is associated with essential hypertension and hypertension." (PMID 40923186, 2025).
breast carcinoma (3 papers, 2018 to 2025). "For example, we found evidence that arterial CALCRL expression, CAD, and breast cancer susceptibility colocalized at the CALCRL locus." (PMID 40874306, 2025). "Intriguingly, samples from breast cancer patients with bone metastases expressed higher CALCRL levels, compared to those with brain, lung, or liver metastases." (PMID 39266299, 2024). "Less is known regarding the chemokinetic effects of CGRP receptors (RAMP1 and CALCRL), although their expression has been demonstrated in several lines of cancer (e.g., prostate and breast cancer)." (PMID 30598641, 2018).
glioblastoma (3 papers, 2019 to 2024). The most malignant astrocytic tumor (WHO grade IV). "Relevant studies have proved that the mRNAs of CALCRL/RAMP2 and CALCRL/RAMP3 are highly expressed in glioblastoma cell lines." (PMID 34712139, 2021). "Furthermore, high levels of CALCRL mRNA were found in human glioblastoma cancer stem-like cells." (PMID 38542389, 2024).
pheochromocytoma (3 papers, 2022 to 2023). "ADM is a potent vasodilator peptide originally isolated from human pheochromocytoma, and its effects are primarily mediated through calcitonin receptor-like receptor (CRLR)." (PMID 35390031, 2022). "Adrenomedullin (ADM) is a potent vasodilator peptide with 52-amino acid residues originally isolated from human pheochromocytoma, and its action is mediated by calcitonin receptor-like receptor (CRLR)." (PMID 35324977, 2022). "In the neoplastic tissues, CALCRL was predominantly expressed in thyroid carcinomas, parathyroid adenomas, small-cell lung cancers, large-cell neuroendocrine carcinomas of the lung, pancreatic neuroendocrine neoplasms, renal clear-cell carcinomas, pheochromocytomas, lymphomas, and melanomas." (PMID 36835377, 2023).
primary angle-closure glaucoma (3 papers, 2009 to 2023). An angle-closure glaucoma characterized by closure of the anterior chamber angle by an intrinsic defect such that aqueous outflow is blocked and the intraocular pressure becomes inappropriately elevated leading to optic nerve damage and visual field loss. "Haplotype association between variants across CALCRL gene and primary angle closure glaucoma in Australian and Nepalese cohorts." (PMID 22933837, 2012).
prostate carcinoma (3 papers, 2021 to 2024). A carcinoma that arises from epithelial cells of the prostate gland. "Similarly, CALCRL gene expression in samples from prostate cancer patients with metastases was higher than expression in benign prostate tissues and primary prostate cancer." (PMID 39266299, 2024). "Similarly, the higher expression of CALCRL was positively associated with metastatic potential in prostate cancer patients, whereas none of RAMPs nor CALCA were." (PMID 39266299, 2024).
uterine fibroids (3 papers, 2017 to 2021). "Using total RNA prepared from our second panel of 26 matched specimens, we confirmed that ESR1, SOX18, CCL5, and PCDH10 but not CALCRL are differentially expressed in uterine leiomyomas or that levels of their expression vary by menstrual phase." (PMID 28637297, 2017).
atherosclerosis (2 papers, 2020 to 2023). A disease characterized by the build-up of fatty material and calcium deposition in the arterial wall resulting in partial or complete occlusion of the arterial lumen. "Our data identify an antiinflammatory signaling pathway in endothelial cells stimulated by disturbed flow and suggest activation of the endothelial adrenomedullin/CALCRL/Gs system as a promising approach to inhibit progression of atherosclerosis." (PMID 33268595, 2020). "This indicates that modulating the endothelial adrenomedullin/CALCRL/Gs system is a more promising approach to inhibit progression of atherosclerosis." (PMID 33268595, 2020). "Additionally, in atherosclerosis, activated Gs-coupled receptor calcitonin receptor-like receptor (CALCRL) induces anti-inflammatory signals and reduces endothelial inflammation." (PMID 37491214, 2023). "The fact that mice lacking adrenomedullin, CALCRL, or Gαs in endothelial cells show an increased progression of atherosclerosis indicates that this signaling pathway is constantly activated in areas of disturbed flow." (PMID 33268595, 2020).
benign breast neoplasms (2 papers, 2023 to 2025). "Our findings revealed that an increase in CALCRL expression correlated with a lower risk of developing benign breast neoplasms (odds ratio [OR], 0.450; 95% CI: 0.313–0.648)." (PMID 40923186, 2025).
colorectal adenocarcinoma (2 papers, 2024). The most common type of colorectal carcinoma. "In this study, the aim was to evaluate the calcitonin gene-related peptide level in colorectal cancer patients’ serum and, together with calcitonin receptor-like receptor, to determine their tumoral levels and toidentify their potential role in the pathogenesis of colorectal adenocarcinomas." (PMID 38674047, 2024).
colorectal cancer (2 papers, 2024). A primary or metastatic malignant neoplasm that affects the colon or rectum. "This study aimed to see whether these neuropeptides and their receptors—neurokinin 1 receptor and calcitonin receptor-like receptor—correlate with the diagnosis stage, tumor differentiation grade, and different patient characteristics in colorectal cancer and also to compare them." (PMID 39337103, 2024).
lung adenocarcinoma (2 papers, 2021 to 2023). A carcinoma that arises from the lung and is characterized by the presence of malignant glandular epithelial cells. "Our bioinformatic analysis identified six downregulated DEGs (EDNRB, RXFP1, P2RY1, CALCRL, TEK, and ANGPT1) between lung adenocarcinoma and normal lung tissues based on two different microarray datasets." (PMID 34039311, 2021).
pancreatic cancer (2 papers, 2016 to 2022). "Expression of CALCRL is undetected in the pancreatic cancer cells while primary human pancreatic stellate and endothelial cells express CALCRL." (PMID 35647198, 2022).
periodontitis (2 papers, 2023 to 2024). An acute or chronic inflammatory process that affects the tissues that surround and support the teeth. "In the Pg sample, we observed interactions between ADM and CALCRL, which is related to periodontitis; EDA and EDA2R, which is related to ectodermal development; and SPP1 and CD44 and SPP1 and (ITGA4+ITGB1), which promotes phosphoprotein secretion and regulates bone salinization." (PMID 37287452, 2023).
Stroke (2 papers, 2025). Sudden impairment of blood flow to a part of the brain due to occlusion or rupture of an artery to the brain. "CALCRL is a protein-coding gene associated with vascular functions; changes in its expression may affect vascular integrity and function, potentially influencing stroke risk." (PMID 40624693, 2025). "In our study, we found a context-dependent or tissue-specific role of CALCRL expression, where its higher genetically predicted expression levels in brain tissues were causally associated with increased WMH burden, and to stroke and AD risk, highlighting a shared cerebrovascular mechanism." (PMID 40799764, 2025).